NDUFB10 (NADH:ubiquinone oxidoreductase subunit B10)
Description:
Accessory subunit that is involved in the functional assembly of the mitochondrial respiratory chain complex I. Complex I has an NADH dehydrogenase activity with ubiquinone as an immediate electron acceptor and mediates the transfer of electrons from NADH to the respiratory chain.
Synonyms: PDSW; MC1DN35
Tractability: Small molecule: an approved drug acts on it; a structure with a bound ligand is known. Antibody: UniProt places it where antibodies can reach, with high confidence. PROTAC: ubiquitination databases record sites on it; its protein half-life has been measured.
Target class: Enzyme; Oxidoreductase
Gene: Protein-coding gene on chromosome 16 (1,959,508 to 1,962,021, forward strand). Ensembl gene ENSG00000140990.
Subcellular location: Mitochondrion inner membrane
Pathways (Reactome):
Metabolism: Complex I biogenesis; Respiratory electron transport
Gene Ontology:
Molecular function: protein binding; NADH dehydrogenase (ubiquinone) activity
Biological process: aerobic respiration; mitochondrial electron transport, NADH to ubiquinone; proton motive force-driven mitochondrial ATP synthesis; proton transmembrane transport
Cellular component: mitochondrial inner membrane; mitochondrion; respiratory chain complex I
Genetic constraint (gnomAD): Loss-of-function variants: 27 observed, 23.68 expected, observed/expected ratio (o/e) 1.14, 90% interval 0.84 to 1.57. The synonymous counts are far from expectation, so gnomAD's model fits this gene poorly and the ratio says little. Missense variants: 312 observed, 228.29 expected, observed/expected ratio (o/e) 1.37, 90% interval 1.25 to 1.5. Synonymous variants: 104 observed, 80.58 expected, observed/expected ratio (o/e) 1.29, 90% interval 1.1 to 1.52.
Gene-disease validity (ClinGen):
ClinGen rates the evidence that NDUFB10 causes each of these diseases.
mitochondrial disease (autosomal recessive): Moderate.
Homologues: Orthologues: chimpanzee NDUFB10 (99% identical), macaque NDUFB10 (87% identical), rat Ndufb10 (82% identical), dog NDUFB10 (81% identical), mouse Ndufb10 (81% identical), pig NDUFB10 (80% identical), guinea pig NDUFB10 (77% identical), tropical clawed frog ndufb10 (63% identical), zebrafish ndufb10 (53% identical), Caenorhabditis elegans ndub-10 (34% identical), Drosophila melanogaster ND-PDSW (28% identical).
Diseases named in the same sentence as NDUFB10 in open-access papers:
NDUFB10 is named in the same sentence as 20 diseases in open-access papers, as found by Europe PMC text mining. Sharing a sentence is not in itself a finding about the gene and the disease. The quoted sentences say what the papers report.
breast carcinoma (1 paper, 2015). "In summary, we discovered novel somatic mutations in the TRPM6, HYDIN, ENTHD1 and NDUFB10 genes in early onset Chinese breast cancer patients through whole exome sequencing." (PMID 26870154, 2015).
Failure to thrive (1 paper, 2020). Failure to thrive (FTT) refers to a child whose physical growth is substantially below the norm. "The first patient reported with an isolated complex I disorder due to a mutation in the human nuclear NDUFB10 gene presented an early‐onset phenotype, characterized by prenatal cardiomyopathy along with metabolic acidosis and failure to thrive." (PMID 32025618, 2020).
Leigh disease (1 paper, 2019). "It is significant in this context that NDUFB10 deficiency has previously been associated with increased mtROS and compromised mitochondrial respiration, while mutations in NDUFA10 have been found in mitochondrial disorders, such as Leigh disease." (PMID 31717900, 2019).
pancreatic cancer (1 paper, 2022). "In this work, we observed that knockout of the NADH dehydrogenase complex subunit genes NDUFB10, NDUFC2, NDUFC2-KCTD14, NDUFS8 led to a decrease in the sensitivity of MIA PaCa-2 pancreatic cancer cells to oxaliplatin." (PMID 35209078, 2022).
tumor (4 papers, 2015 to 2025). "Within the validated mutations, somatic mutations in the TRPM6, HYDIN, ENTHD1, and NDUFB10 genes were found in two or more tumor samples in the replication stage." (PMID 26870154, 2015). "In addition, we found that many genes associated with ATP synthesis, such as ATP5F1D, ATP5ME, and ATP5MF, and genes associated with NADH oxidation, such as NDUFS8, NDUFB10, and NDUFC1, were overexpressed in LIHC and LUAD tumor tissues." (PMID 33262783, 2020).
cancer (2 papers, 2015 to 2024). A tumor composed of atypical neoplastic, often pleomorphic cells that invade other tissues. "Phosphorylation of NDUFB10 by Src kinase could participate in the development of the proliferative phenotype of glycolytic cancer cells, such as 143B and DU145 cells by preserving complex I activity." (PMID 26870154, 2015).
mitochondrial disease (1 paper, 2021). "NDUFB10 is a vital subunit of complex I and a patient with compound heterozygous mutations in NDUFB10 presented with symptoms of mitochondrial disease, defects in late stage complex I assembly, and reduced complex I activity." (PMID 33640490, 2021).
NDUFB10 also shares sentences with these, for which no sentence is quoted: cardiomyopathy (2 papers); lactic acidosis (2); Alpers' disease (1); Alzheimer disease (1); brain diseases (1); fibrosis (1); Huntington disease (1); Hypertension (1); metabolic acidosis (1); neurological diseases (1); Nonalcoholic fatty liver disease (1); Parkinson disease (1); renal carcinoma (1).